IL6 (interleukin 6)
Diseases named in the same sentence as IL6 in open-access papers (continued):
Sharing a sentence is not in itself a finding about the gene and the disease.
macrophage activation syndrome (87 papers, 2014 to 2025). A complication of rheumatic disease that is caused by excessive activation and uncontrolled proliferation of T lymphocytes and well-differentiated macrophages. "It is characterized by hyperactivation of the IL-1/IL-6 signaling pathways, increased levels of endogenous Toll-like receptor ligands such as S100 proteins, and a heightened susceptibility to macrophage activation syndrome (MAS)." (PMID 40948862, 2025). "IL-6: COVID-19 infections can cause cytokine storm and macrophage activation syndrome (MAS), due to the hyper-activated T lymphocytes with the release of different inflammatory cytokines, including IL-6." (PMID 35466178, 2022). "The G allele may serve as a risk factor for elevated serum IL-6 levels and progression to macrophagic activation syndrome." (PMID 38783290, 2024). "The pathogenesis of SJIA is complex, with an autoinflammatory presentation involving proinflammatory cytokines such as interleukin (IL)-1 and Il-6, a risk of life-threatening macrophage activation syndrome (MAS) in some patients also involving other cytokines, such as interferon gamma and IL-18." (PMID 35268449, 2022). "Kerget and Kerget, 2021 found significant difference between NON-MAS (macrophage activation syndrome) and MAS (macrophage activation syndrome) groups as regards IL-6-174G/C polymorphism and this was accompanying with higher IL-6 levels." (PMID 39354444, 2024). "High levels of IL-6 in serum may contribute not only to a cytokine storm, but even to macrophage activation syndrome (MAS): a severe inflammation caused by activated macrophages, manifested by fever, hyperferritinemia, hypofibrinogenemia, coagulopathy and cytopenia." (PMID 33920709, 2021). "Cytokine dysregulation, particularly involving IL-1 and IL-6, plays a central role in its pathogenesis, and complications such as macrophage activation syndrome (MAS) and interstitial lung disease (ILD) can be observed." (PMID 40370972, 2025). "Macrophage activating syndrome (MAS) and increased levels of interleukin-6 (a pro-inflammatory cytokine) associated with cytokine storm in the inflammatory phase of COVID-19 infection are known to be involved in the pathogeneses of multiorgan damage." (PMID 37322551, 2023). "Among the Th2 cytokines, IL-6 can trigger a “cytokine storm” (known as cytokine release syndrome), as well as macrophage activation syndrome." (PMID 36614125, 2022). "It has been suggested that IL-6 promotes a macrophage activation syndrome (MAS), triggering mass production of pro-inflammatory cytokines and inducing migration of neutrophils and fibroblasts into the pulmonary epithelium." (PMID 35784888, 2022). "These side effects are caused by cytokine secretion (e.g. IL-1, IL-6) due to immune cell and target interactions, which initiate cytokine release syndrome (CRS), macrophage activation syndrome (MAS) and neurotoxic symptoms." (PMID 34012442, 2021). "SARS-CoV-2 increases interferon gamma, tumor necrosis factor-α, macrophage inflammatory protein-1 alpha, IL-2, IL-6, IL-7, IL-10, in patients, that show a form of secondary hemophagocytic lymphohistiocytosis or macrophage activation syndrome (sHLH/MAS)." (PMID 33494816, 2021). "Pediatric dosing experience exists with corticosteroids and interleukin 1 receptor antagonist protein (Systemic Juvenile Arthritis induced Macrophage Activation Syndrome) and interleukin 6 inhibitors (CAR T-cell therapy induced Cytokine Releasing Syndrome)." (PMID 32634818, 2020). "IL-6, along with other inflammatory cytokines like TNF-α, IL-1β, and IFN-γ is associated with more severe cases involving macrophage activation syndrome and adult respiratory distress syndrome." (PMID 33324210, 2020).
macrophage activation syndrome (continued). "This algorithm poses a particular alert to patients with morphological residual disease receiving CAR T-cells for the higher risk of sCRS, likely in virtue of interleukin-6, production by monocytes/macrophages after phagocytosis of tumor debris, (macrophage activation syndrome, or MAS)." (PMID 26110321, 2015). "sJIA has many characteristics of an autoinflammatory pathology, associated with an increased synthesis of pro-inflammatory interleukins such as IL-1, IL-6, and IL-18, as well as S100 proteins; at the same time, in its evolution, sJIA can be complicated by macrophage activation syndrome (MAS)." (PMID 36361547, 2022). "Compared with moderate cases, severe cases show markedly higher circulating levels of tumor necrosis factor-α (TNF-α), interleukin-6 (IL-6), IL-10, and the soluble form of IL-2 receptor, exhibiting features similar to those of cytokine storm syndromes, such as macrophage activation syndrome." (PMID 33644468, 2021). "The cytokine profile in these studies is comparable to that reported in cytokine release syndromes, such as macrophage activation syndrome, which is characterized by increased expression of cytokines (IL6, IL7, and TNF) and inflammatory chemokines (CCL2, CCL7, CXC-10, and CXCL-11)." (PMID 35145507, 2021). "Recent studies have also revealed that excessive IL-6 signaling leads to hypercoagulating, megakaryocyte activation, precipitation of pulmonary immune-mediated thrombosis, induction of macrophage activation syndrome, and reduction of myocardium contractility, which might contribute to organ damage." (PMID 34046036, 2021). "This is primarily due to the immune dysregulation or macrophage activation syndrome of SARS-CoV-2, both characterized by pro-inflammatory cytokines, where immune dysregulation is driven by IL-6." (PMID 40376291, 2024). "Macrophage activation syndrome (MAS) development, one of the characteristics of a cytokine storm, depends on inflammatory cytokines such as TNF-α and IL-6." (PMID 35466278, 2022). "Hyperinflammation and macrophage activation syndrome (MAS) result in the overproduction of proinflammatory cytokines, such as the IL-1β, IL-6, and TNFα, as well as coagulation abnormalities, which contribute to organ failure and other fatalities." (PMID 35495698, 2022). "Cytokine storm, defined as macrophage activation syndrome (MAS), is characterized by the release of multiple pro-inflammatory cytokines (IL-1β, IL-18, IL-6, IL-2, IL-7, TNF-α) and chemokines (CCL2, CCL3) from macrophages." (PMID 35008658, 2021). "In one study (n = 70), with patients belonging to two groups, severe (high IL-6 and macrophage activation syndrome - MAS), and non-severe (no-MAS, low IL-6), G allele is significantly associated with MAS." (PMID 34775962, 2021). "Macrophage Activation Syndrome (MAS) is a hyperinflammatory syndrome characterized by CRS, cytopenia and multiorgan failure in which IL-6 and ferritin level are particularly elevated." (PMID 33353549, 2020). "Careful observation revealed that the excessive cytokines and chemokines activated by macrophages (i.e., IL-6, IL-7, TNF-α, CCL-2/MCP-1, CCL-3/MIP-1α) were similar to results previously found in hemophagocytic lymphohistocytosis (HLH) and macrophage activation syndrome (MAS)." (PMID 32922406, 2020). "The pathophysiology of DM RP-ILD could be similar to that of macrophage activation syndrome (MAS), in which a variety of cytokines (e.g., interleukin (IL)-1, IL-6, tumor necrosis factor (TNF)-α) are involved." (PMID 30367666, 2018). "However, severe CRS cases, particularly those complicated by secondary hemophagocytic lymphohistiocytosis/macrophage activation syndrome (HLH/MAS), may be refractory to IL-6 inhibition and require more aggressive immunosuppressive interventions, including chemotherapy." (PMID 41347097, 2025).
macrophage activation syndrome (continued). "Furthermore, TCZ was shown to be efficacious in patients with reactive HLH or macrophage activation syndrome (MAS) in a few case reports, suggesting that IL-6 blockade could be a potential therapeutic target in sHLH." (PMID 36131317, 2022). "Driven by innate immune dysregulation and overproduction of proinflammatory cytokines (IL-1, IL-6, IL-18), AOSD presents in systemic and articular phenotypes, with severe complications like macrophage activation syndrome (MAS), fulminant hepatitis, and parenchymal lung disease." (PMID 41607599, 2025). "Moreover, it may elevate other proinflammatory cytokines, including IL-6, IL-8 and IL-10, generated by other bystander immune cells, resulting in even more severe hyperactive immune disorders, hemophagocytic lymphohistiocytosis (HLH) and macrophage activation syndrome (MAS)." (PMID 35432345, 2022). "The IL-6 levels we and others have observed do not differentiate MIS-C from other inflammatory conditions, like macrophage activation syndrome, hemophagocytic lymphohistiocytosis, or Kawasaki disease with shock." (PMID 34869111, 2021).
Shock (87 papers, 2005 to 2026). The state in which profound and widespread reduction of effective tissue perfusion leads first to reversible, and then if prolonged, to irreversible cellular injury. "Supporting its emerging role as a predictor of adverse outcome, the associated inflammatory cytokines TNF-α, IL-6 and IL-1Ra had significantly higher values in patients with MI complicated with cardiogenic shock than in those with a more favourable evolution." (PMID 35204357, 2022). "We then analyze plasma from patients with septic shock and find that increasing levels of IL-6 and blaTEM are associated with mortality, while decreasing IL-6 levels are associated with recovery." (PMID 32451375, 2020). "We therefore speculate that the increased bleeding in anemic mice was associated with more pronounced sequelae of hemorrhagic shock associated with evolution of higher IL-6 levels and susceptibility to unabated inflammation, contributing to death." (PMID 39286605, 2024). "In addition, in the absence of AhR in macrophages, mice are more susceptible to LPS-induced endotoxic shock and present with an increase in pro-inflammatory IL-6 expression." (PMID 31722204, 2019). "Cardiogenic shock is associated with systemic inflammation and multiorgan failure; convincing data were obtained on the correlation between shock severity and elevated levels of highly sensitive C-reactive protein, interleukin-1b, interleukin-6, and tumor necrosis factor alpha." (PMID 38137809, 2023). "In acute HF, IL-6 levels measured 48–72 h after admission were independently predictive of 30-day mortality, and patients with cardiogenic shock exhibited an early surge in IL-6 levels." (PMID 40868877, 2025). "The period of septic shock onset and progression was marked by progressive decline in IL-6 and MIP-2, and progressive increase in TNF-α and IL-10." (PMID 41155249, 2025). "sRAGE also promotes hepatic regeneration and restricts bacterial translocation to lymph nodes during hemorrhagic shock and downregulates IL-6." (PMID 39682695, 2024). "PCT, IL-6, SIRS, NEWS, qSOFA, and surgical time were identified as independent risk factors for septic shock." (PMID 38849783, 2024). "Candidates for sequential HA include patients experiencing septic shock, multiorgan dysfunction, elevated endotoxemia, and hypercytokinemia (particularly extremely high levels of IL-6)." (PMID 38391573, 2024). "In septic shock, interleukins are the first to increase, reaching a maximum peak at 2 h, when procalcitonin increases, and IL-6 and IL-8 levels decrease." (PMID 38068931, 2023). "Other research demonstrated that patients with septic shock who had higher levels of interleukin-6 (IL-6) at baseline were more likely to benefit from early goal-directed therapy." (PMID 37509441, 2023). "Recent literature data show that IL-6 is one of the biomarkers involved in severe inflammatory syndrome, but a more detailed analysis shows that its value is lower in bacterial septic shock." (PMID 37241099, 2023). "Our results, therefore, underscore the important role of IL6 signaling pathways in polytrauma, with haemorrhagic shock being a major trigger of the inflammatory response." (PMID 36151360, 2023). "In conclusion, APACHE II score, IL-6, and NSE were associated with the ICU mortality of patients with septic shock." (PMID 36221401, 2022). "Patients with septic shock present higher IL-6 and IL-8 plasma levels and lower levels of IFNγ than patients with infection, showing that an impaired immune response contributes to a worse prognosis." (PMID 36536294, 2022). "Concentrations of IL-6 are elevated in conditions such as surgical stress, trauma, multiple organ failure, and septic shock and peak after TNF-α and IL-1." (PMID 32232117, 2020).
Shock (continued). "It is noteworthy that a previous study showed that in vitro exposure to TNF-α or IL6 isolated from serum of humans with septic shock induced depression of rat cardiac myocyte contractile function, and these two factors appeared to have a synergistic effect." (PMID 26812689, 2016). "In patients with septic shock, IL-6 levels have been shown to correlate with disease severity and outcome." (PMID 22889197, 2012). "Plasma IL-6 levels were elevated in patients with septic shock and plasma levels significantly correlated with the severity of myosin loss." (PMID 21958504, 2011). "We measured serum levels of IL-6, IL-8, sELAM-1 and sICAM-1 in 40 intensive care unit patients who developed septic shock." (PMID 16137344, 2005). "Furthermore, t-test analyses revealed a decreased proinflammatory cytokine IL-1, while mRNA levels of TNF-α and IL-6 were unaltered by foot-shock." (PMID 39544929, 2024). "Likewise, elevated IL-6, IL-8, and TNF-α concentration are associated with septic shock and multiple organ failure." (PMID 38068931, 2023). "Furthermore, our results show maximal impairment of CYP1A2 activity measured with LiMAx® 24 h after the start of CytoSorb® treatment, especially in patients with septic shock and extremely elevated IL-6 levels." (PMID 36289602, 2022). "Likewise, the additional hemorrhagic shock in our experimental mouse model leads to an overexpression of genes involved in the positive regulation of IL-6 production." (PMID 33574730, 2021). "Remarkably, IL-6 plasma concentrations in MIS-C were lower than in children with septic shock." (PMID 34869111, 2021). "In addition, anti-inflammatory effect of IFN-β through SIRT1 upregulation and down regulation of inflammatory cytokines including IL-6 has been investigated in lethal endotoxic and septic shock." (PMID 29423066, 2018). "We found that, in the early phase of septic shock, plasma IL-6 (obese 106, IQR 34 to 686; overweight 190, IQR 44 to 2,339; BMI of less than 25 kg/m2 235, IQR 44 to 1,793 pg/mL; P = 0.046) levels were significantly lower in obese and overweight patients than in those with a BMI of less than 25 kg/m2." (PMID 23786836, 2013). "IL-6 levels can rise in virtually any inflammation, even during exercise by releasing IL-6 from skeletal muscle, or even after multiple traumas (proportional trauma), reaching micrograms per milliliter (μg/mL) values under severe conditions such as septic shock." (PMID 34356982, 2021). "APACHE II score, IL-6, Lac, TBil, NSE (day1), and NSE (day4) showed a weak positive correlation with ICU mortality in patients with septic shock (all P < .05)." (PMID 36221401, 2022). "The AUCs of APACHE II score, IL-6, NSE (day1), and NSE (day4) for predicting prognosis in patients with septic shock were 0.650 (95%CI 0.531–0.757), 0.694 (95%CI 0.577–0.795), 0.758 (95%CI 0.646–0.850) and 0.770 (95%CI 0.658–0.859), respectively (all P < .05)." (PMID 36221401, 2022). "LPS-induced endotoxic shock in ANXA1–/– mice was also correlated with increase in TNFα, IL-1 and IL-6 levels in the blood when compared with wild-type mice." (PMID 27540524, 2016). "In summary, this study revealed the critical involvement of the IL-6/JAK/STAT3, PI3K/Akt/mTOR, and TNF-α/NF-κB pathways in pediatric postoperative septic shock and identified key genes such as PIM3, with quercetin and astramembrannin I predicted as potential therapeutic compounds." (PMID 41189212, 2025). "Both subsets are released from the bone marrow after stimulation with various inflammatory/infectious signals such as G-CSF and IL-6 which were more increased after VA-ECMO initiation compared to patients with cardiogenic shock without ECMO." (PMID 33407728, 2021). "In this patient population with predominantly septic shock and multiple organ failure, hemoadsorption removed IL-6 but this did not lead to lower plasma IL-6-levels." (PMID 29084247, 2017).
Shock (continued). "We documented the early time course evolution of circulatory Prdx1, hypoxic marker carbonic anhydrase IX, inflammatory cytokines including IL-6, IL-8, IL-10, MCP-1, TNF-α, IL-1β, and danger signaling receptors (TLR4 and CD14) in a cohort of cardiogenic shock patients within 1 day after ECMO support." (PMID 27142532, 2016). "Similarly, VPA showed protection from lung inflammation by decreasing serum IL-6 and TNF-α levels, as well as MPO activity significantly in pulmonary tissue by amelioration of lung damage in a rat model of septic shock or acute lung injury." (PMID 25938838, 2015). "Once bacterial dose and infusion-rate optimization was achieved, all sheep developed septic shock (as per Sepsis 3 criteria) within 12 h of completion of E. coli infusion, with corresponding increases in the vasopressor requirement (VDI) and cytokines (IL-6, IL-8, IL-10, and VEGFA)." (PMID 39467921, 2024). "Reduced levels of IL-1β, TNF-α and IL-6 were detected in the NLRC4-siRNA group, compared with the sham and NC-siRNA groups (all pCLP vs. NLRC4-siRNA < 0.001; pNC-siRNA vs. NLRC4-siRNA < 0.001), which suggested that NLRC4 gene silencing alleviated the inflammatory reaction induced by septic shock." (PMID 33406504, 2021). "Moreover, patients with NSTI and septic shock at baseline had significantly higher levels of IL-1β, IL-6, IL-10 and TNF-α level than in patients with NSTI without shock." (PMID 28176831, 2017).